RNF43 (ring finger protein 43)
Diseases named in the same sentence as RNF43 in open-access papers (continued):
Sharing a sentence is not in itself a finding about the gene and the disease.
ovarian tumors (3 papers, 2014 to 2024). "Loss of wild‐type RNF43 by LOH or second‐hit somatic mutations has been reported in ovarian tumors and serrated colon tumors, suggesting the need for two‐hit inactivation of RNF43 for tumorigenesis." (PMID 35040131, 2022). "Intriguingly, we also detected a marked elevation in the expression of KIAA1199 and RNF43 in CD151-deficient ovarian tumor cells, two newly identified negative regulators of Wnt signaling, implying a potential feedback mechanism related to CD151 function." (PMID 25356755, 2014). "When BRCA2mt ovarian tumors were compared with BRCA1mt tumors, eight genes (NOTUM, SFRP5, RNF43, ZNRF3, DKK1, DKK4, NKD1, and AXIN2) that negatively regulate Wnt signaling were upregulated in BRCA2mt tumors." (PMID 39028933, 2024).
adrenocortical cancer (2 papers, 2023 to 2025). "The results suggested that RNF43 might exert various biological functions, including the detection of chemical stimulus, detection of stimulus involved in sensory perception, and sensory perception of chemical stimulus in diverse cancer types, such as adrenocortical cancer (ACC) and LUAD." (PMID 37848933, 2023).
Influenza infection (2 papers, 2015 to 2019).
intestinal tumors (2 papers, 2022 to 2025). "Mouse genetic studies have shown that the simultaneous disruption of Rnf43 and Znrf3 in the intestine results in Wnt ligand‐independent growth and development of intestinal tumors through Wnt signaling activation." (PMID 35040131, 2022).
tubular adenoma (2 papers, 2022 to 2024). A usually polypoid neoplasm arising from the glandular epithelium. "No KRAS or RNF43 variants were detected among the four lesions, including tubular adenomas." (PMID 36419139, 2022). "Sanger sequencing of the BRCA1 and RNF43 variants in the tubular adenoma, SSL and CRC from person 010 showed evidence of LOH of the wildtype allele for both variants in the SSL and adenocarcinoma but not the tubular adenoma." (PMID 38063999, 2024).
ampullary cancer (1 paper, 2020). "The most frequent gene alteration in ampullary cancer was found in APC (23%), followed by CTNNB1 (9%), RNF43 (8%), CDH1 (1.9%), and WNT1 (1.3%)." (PMID 32764696, 2020).
bladder cancers (1 paper, 2022). "RNF43 mutations were strongly associated with improved overall survival in the colorectal and bladder cancer cohorts, surpassing the relationship between survival and total mutational burden in these patients." (PMID 35798829, 2022). "In addition to TET1, our study also identified mutations affecting the E3 ubiquitin-protein ligase RNF43 as a potential predictor of therapeutic responses, notably for colorectal and bladder cancer patients." (PMID 35798829, 2022).
breast tumor (1 paper, 2025). "We next examined whether RNF43 silencing contributes to RCOR2-induced breast tumor plasticity." (PMID 40608411, 2025).
colitis (1 paper, 2025). Inflammation of the colon. "Furthermore, RNF43-mutated were frequent (12.9%) in precancerous lesions of ulcerative colitis (UC) patients and detectable in 24.4% of colitis-associated cancer patients." (PMID 40860811, 2025).
cystic neoplasm (1 paper, 2025). A benign or malignant neoplasm that contains a single or multiple cystic spaces. "However, the most common molecular alterations found in ductal adenocarcinoma (KRAS), cystic neoplasms (GNAS and RNF43), and NENs (MEN1, DAXX, and ATRX) are rarely found in ACC." (PMID 41120769, 2025).
familial colorectal cancer type X (1 paper, 2024). Hereditary nonpolyposis colorectal cancer characterized by the absence of germline mutations in DNA mismatch-repair genes. "Remarkably, this report showed that pathogenic mutations in both BRCA1 and RNF43 were inherited together and were associated with CRC in a family with a specific type of familial CRC known as familial colorectal cancer type X (FCCTX)." (PMID 39195204, 2024).
gallbladder adenocarcinoma (1 paper, 2022). A carcinoma that arises from glandular epithelial cells of the gall bladder. "Furthermore, alterations could be found in Ring finger protein 43 (RNF43) in 1 CCA cell line (R117H, SG231) and 2 CCA tissue samples (R337Q/iCCA and E187*/gallbladder adenocarcinoma)." (PMID 36013219, 2022).
glioblastoma (1 paper, 2023). The most malignant astrocytic tumor (WHO grade IV). "On the contrary, RNF43 was decreased in glioblastoma multiforme (GBM), kidney chromophobe (KICH), kidney renal clear cell carcinoma (KIRC), kidney renal papillary cell carcinoma (KIRP), and pheochromocytoma and paraganglioma (PCPG) compared to the normal tissues." (PMID 37848933, 2023).
hepatitis B (1 paper, 2024). "We also detected the expression of FOSB, GPAT3, RGCC, and RNF43 in the blood of patients with hepatitis B, hepatitis C and AIH." (PMID 38965537, 2024). "The results showed an increased expression of FOSB in patients with hepatitis B, an increased expression of RNF43 in patients with hepatitis C, and an increased expression of RNF43 along with a decreased expression of RGCC in patients with AIH." (PMID 38965537, 2024). "We also examined FOSB, GPAT3, RGCC, and RNF43 expression in patients with hepatitis B, hepatitis C, and AIH." (PMID 38965537, 2024). "In addition, FOSB is reported to be related to hepatitis C, while RNF43 and GPAT3 are related to hepatitis B." (PMID 38965537, 2024).
hereditary cancer (1 paper, 2024). Malignant neoplasms occurring in families at a rate greater than that expected by chance and caused by germline mutations in a specific gene. "Germline genetic testing was performed with a gene panel consisting of 46 genes related to hereditary cancer and a nonsense variant in RNF43 (c.1948 C > T, p.(Arg650Ter)) was identified." (PMID 39546056, 2024).
intestinal polyp (1 paper, 2022). Discrete abnormal tissue masses that protrude into the lumen of the intestine. "As an example of this scenario, we found additional RNF43 variants in the intestinal polyp we analyzed." (PMID 35075588, 2022).
Leukoencephalopathy (1 paper, 2010). This term describes abnormality of the white matter of the cerebrum resulting from damage to the myelin sheaths of nerve cells. "Downregulated genes included amyloid beta precursor protein‐binding, family a member 2 (APBA2); glycoprotein m6a (GPM6A); megalencephalic leukoencephalopathy with subcortical cysts 1 (MLC1); ankyrin repeat and btb domain containing 2 (ABTB2); and ring finger protein 43 (RNF43)." (PMID 19793339, 2010).
low grade glioma (1 paper, 2019). A grade I or grade II glioma arising from the central nervous system. "Some studies have shown decreased RNF43 expression correlated with poor prognosis in GBM and low grade glioma (LGG) patients, while high expression of CPEB4 was associated with shorter OS rates." (PMID 31692451, 2019).
medulloblastoma (1 paper, 2025). A malignant, invasive embryonal neoplasm arising from the cerebellum. "ElasticNet coefficients highlighted the predictive importance of genes such as AXIN1, RNF43, STK3, LEF1, and DKK1 for identifying the WNT subtype status in this medulloblastoma validation cohort." (PMID 39851951, 2025).
metastatic melanoma (1 paper, 2021). A melanoma that has spread from its primary site to another anatomic site. "RNF43 is a β-catenin target gene, which could be a reason for the low RNF43 levels in metastatic melanomas where Wnt/β-catenin signaling is inhibited." (PMID 34702444, 2021).
mucinous adenocarcinoma (1 paper, 2021). An invasive adenocarcinoma composed of malignant glandular cells which contain intracytoplasmic mucin. "Our results showed that KRAS was the main mutated gene in appendiceal mucinous adenocarcinoma, especially in exon 2 (4/9 cases), followed by RNF43 (3/9)." (PMID 33712927, 2021). "One case of appendiceal mucinous adenocarcinoma had BRAF p.V600E mutation and alteration in the RNF43 gene with stable expression of MMR proteins." (PMID 33712927, 2021). "Yanai and colleagues recently suggested RNF43 mutations may occur at a later stage of mucinous adenocarcinoma development and may not be associated with PMP." (PMID 33712927, 2021).
mucinous tumours (1 paper, 2020). "Brenner tumour‐associated mucinous tumours demonstrated rare SATB2 expression and more frequently calcifications and Walthard cell nests, whereas teratoma‐associated mucinous tumours showed high SATB2 expression and RNF43 mutations and were closely resembled true gastrointestinal tumours." (PMID 32885593, 2020).
neuroblastoma (1 paper, 2023). Neuroblastoma (NB) is the most common solid, extracranial childhood tumor. "The neuroblastoma cell line SK-NA-S only expresses LGR5 as shown by us and others, and RNA-seq data showed no or little expression of LGR4, LGR6, RNF43, or ZNRF320,35." (PMID 37402772, 2023).
Obesity (1 paper, 2024). Accumulation of substantial excess body fat. "We identified significant HFD-induced hypermethylation at three loci (#13, #15 and #25) in RNF43 owing to HFD-induced obesity." (PMID 38622664, 2024).
sarcoma (1 paper, 2023). A usually aggressive malignant neoplasm of the soft tissue or bone. "Weakly positive RNF43 expression was detected in sarcoma patients." (PMID 37848933, 2023).
schizophrenia (1 paper, 2022). A major psychotic disorder characterized by abnormalities in the perception or expression of reality. "We further confirmed the hyperactivation of Wnt/β-catenin pathway in the OPCs, from the hippocampus of schizophrenia patients, by detecting an increased immunoreactivity of Wnt downstream gene RNF43 (181.4 ± 30.5% increase)." (PMID 36131044, 2022).
signet ring cell carcinoma (1 paper, 2021). A usually aggressive, poorly differentiated invasive adenocarcinoma characterized by the presence of malignant glandular cells in which the nucleus is pressed to one side by the presence of intracytoplasmic mucus. "In fact, the signet-ring cell carcinoma, a rare subtype of CRC with a high (34.5%) RNF43 mutation rate, actually showed significantly inhibited Wnt/β-catenin signaling than those without RNF43 mutations." (PMID 34000297, 2021).
skin cancer (1 paper, 2023). "Mutations in ZNRF3 are found in both uterine and skin cancers, but have been studied less frequently than RNF43 mutations." (PMID 37048063, 2023). "RNF43 is mutated in uterine, colorectal, pancreatic, stomach, and skin cancer." (PMID 37048063, 2023).
thymoma (1 paper, 2023). A neoplasm arising from the epithelial cells of the thymus. "The results suggested that RNF43 was negatively correlated with the immune score in COAD (p < 2.2e-16), KIRC (p = 1.4e-14), LIHC (p < 7.8e-12), thymoma (THYM) (p = 4.7e-10) and UVM (p = 0.0021), but was positively correlated with the immune score in DLBC (p = 0.01)." (PMID 37848933, 2023).
tubular adenocarcinoma (1 paper, 2023). An infiltrating adenocarcinoma in which the malignant cells form tubular structures. "In the case of an identified BRAF and RNF43 somatic mutation, despite the tumor being in the right side of the colon, it was an early tubular adenocarcinoma." (PMID 36734304, 2023).
uveal melanoma (1 paper, 2023). A melanoma derived from melanocytes of the uveal tract. "Furthermore, our results revealed that RNF43 was significantly associated with the clinical stage in 4 cancer types, in which RNF43 expression levels were lower in later clinical stages, including KIRC, KIRP, THCA, and uveal melanoma (UVM)." (PMID 37848933, 2023).
tumor (166 papers, 2015 to 2026). "Although ZNRF3 shows little homology with RNF43 in its C-terminal domain, we tested three tumor-associated truncating mutations reported in the equivalent ZNRF3 region (G612tr, G619tr, Q657tr)." (PMID 39674817, 2025). "In our previous research, we established the role of RNF43 mutations in the tumor microenvironment of patients with microsatellite instability." (PMID 40368902, 2025). "The platform was also used to explore survival outcomes based on tumor stage among RNF43-mutated CRC patients." (PMID 40860720, 2025). "Reduced tumor initiation frequency by RCOR2 loss in mice was also rescued when RNF43 was co-deleted." (PMID 40608411, 2025). "RNF43 expression is associated with the tumor-node-metastasis stage, distant metastasis, and survival rate of patients with GC, with decreased RNF43 expression supporting the cancer stem cell-like maintenance of GC cell lines." (PMID 41487817, 2025). "A defining strength of AI-HOPE-WNT lies in its ability to dynamically stratify CRC patient cohorts by WNT gene mutation status (e.g., APC, AXIN1/2, RNF43), tumor location, age group, treatment exposure (e.g., FOLFOX), and molecular phenotype (e.g., MSI)." (PMID 40860720, 2025). "Patients with an RNF43-mutated tumour were more likely to have a V600BRAF mutation compared to patients who were RNF43 wild type (98% vs. 79%, p = 0.02)." (PMID 41002577, 2025). "BI-905677 exhibited antitumor activity in preclinical trials, such as the ring finger protein 43 (RNF43) mutation tumor model and R-spondin 1 (RSPO) fusion tumor model." (PMID 40176913, 2025). "Single-cell sequencing revealed that RNF43-deficient tumor progression was accompanied by complex Immunological change, demonstrating low myeloid and high lymphocyte TME." (PMID 39744438, 2025). "It strongly suppresses Wnt signals in healthy conditions and various genetic mutations in RNF43 are identified in many cancers; thus, RNF43 mutations are thought to be deeply involved in carcinogenesis as a tumor suppressor gene." (PMID 38383910, 2024). "RNF43 effectively inhibits Wnt signals in healthy circumstances, and numerous genetic mutations in RNF43 present in many cancers delineate a tumor suppressor type of carcinogenesis." (PMID 39125653, 2024). "Focusing on this HLA-intact population (n = 58), tumours with RNF43 fs mutations had significantly higher CD8+ T cell infiltration than those without it, which seems to be consistent with previous studies demonstrating that neoantigens induce an inflamed TME." (PMID 36732592, 2023). "RNF43 is a tumor suppressor gene, and loss-of-function mutations in RNF43 often accompany GNAS mutations during IPMN development." (PMID 37470859, 2023). "Previous investigations showed that reduced RNF43 expression in tumor cells is associated with increased cell proliferation and increased invasive capacity, and reduced or lost expression of RNF43 predicts poor survival." (PMID 36823311, 2023). "Tumours with neoantigens derived from these RNF43 fs mutations tended to have an inflamed TME, which is consistent with the neoantigen theory." (PMID 36732592, 2023). "We identified frameshift mutations in RNF43 as a common neoantigenic gene mutation in MSI-H tumours." (PMID 36732592, 2023). "For instance, in a mouse model of WNT-dependent CRC with intestine-specific mutations of Rnf43 and Znrf3, a Wnt3 secreting niche provided by Paneth cells was necessary to maintain tumor growth." (PMID 36982422, 2023). "The HPA008079, ab84125 and ab217787 antibodies have been commonly used on formalin-fixed and paraffin embedded (FFPE) tissue sections, among others to show loss or retainment of RNF43 protein expression in tumor samples." (PMID 37023034, 2023). "Particularly, RNF43 has been established as a tumor suppressor gene, negatively regulating the Wnt signaling pathway and mutations of RNF43 occur in as many as 3–44% of GCs6." (PMID 36823311, 2023).
tumor (continued). "In the same sense, CCA patients with tumors bearing inactivating mutations or downregulation of RNF43 have less favorable outcomes, supporting the consideration of RNF43 as a tumor suppressor gene." (PMID 37190050, 2023). "Nevertheless, we proposed that RNF43 mutation affects the genomic features of BRAF mutant CRC tumours and it can be used as a potential specific marker for future application." (PMID 37409251, 2023). "For instance, tumours with RNF43 or RSPO mutations, still require exogenous WNT ligands to drive WNT signalling (ligand-dependent mutations)." (PMID 37048063, 2023). "Recent work showed that RNF43 is associated with aggressive tumor biology along with BRAF mutation in right sided CRC18, further supporting a distinct pathogenic mechanism and regional preference for Wnt pathway alterations." (PMID 35907983, 2022). "25‐OHC treatment lessons Fzd5‐dependent Wnt/β‐catenin signaling and causes the mitigation of the tumor burden of RNF43‐mutant PDAC." (PMID 35975457, 2022). "No such classical activating mutations have been found in ICC genome sequencing (with the exception of rare RNF43 mutations) despite a number of descriptions of ICC being a Wnt-high tumor." (PMID 35074757, 2022). "The near-universal loss of APC in CRC renders tumours Wnt ligand-independent, bypassing the regulatory activities of RNF43 and ZNRF3." (PMID 36131013, 2022). "This expanding cluster contained two missense variants of consequence, a K/N substitution in the receptor tyrosine kinase DDR2 as well as a splice-site variant in the tumor suppressor RNF43." (PMID 34016182, 2021). "Five tumor suppressor genes have variants (RNF43 G659fs, NPM1 W288fs, RPL22 K15fs, ACVR2A K437fs, LARP4B T163fs) that occur in over 5% of samples in at least one cohort." (PMID 34214079, 2021). "Loss-of-function mutations in RNF43 promotes tumor cell proliferation and result in neoplastic transformation." (PMID 34149925, 2021). "RNF43 is another protein exerting a tumor suppressor activity; its mutations have been described in IPMN." (PMID 34884643, 2021). "Mutations in RNF43 have been reported in several neoplasms, including colorectal cancer (18.9%) and endometrial cancer (18.1%)." (PMID 35008235, 2021). "Recurrent RNF43 mutations are predicted to create neopeptides and have been associated with aggressive tumor biology." (PMID 34214079, 2021). "Mutations of RNF43 have been reported in several neoplasms, including colorectal cancer, endometrial cancer, and mucinous cystic neoplasms of the pancreas (MCN)." (PMID 32934653, 2020). "In summary, we identified a class of RNF43 mutations that mediate a tumor suppressor‐to‐oncogene switch to drive downstream Wnt pathway activation." (PMID 32965059, 2020). "Frequent mutation of the tumour suppressor RNF43 is observed in many cancers, particularly colon malignancies." (PMID 32934222, 2020). "RNF43 encodes a ubiquitin E3 ligase that reduces the level of frizzled receptor and acts as a tumor suppressor in the Wnt signaling pathway." (PMID 32934653, 2020). "Lastly, ERBB3 and SMAD4 mutated tumors had a significantly higher infiltration of mDCs in the tumor and stromal compartments, and RNF43 mutated tumors had a significantly higher infiltration of iDCs in the tumor compartment." (PMID 33013928, 2020). "This study also showed that most RNF43 mutations (73%–75% of non-silent mutations) found were truncating, confirming that RNF43 acts as a tumor suppressor." (PMID 31382613, 2019). "Apart from the advanced tumor stage that is associated with low RNF43 expression, RNF43 normally inhibits chemotherapy resistance in vitro, and this protective mechanism is eliminated by the loss of RNF43." (PMID 31248166, 2019).